STAT5A (signal transducer and activator of transcription 5A)
Diseases named in the same sentence as STAT5A in open-access papers (continued):
Sharing a sentence is not in itself a finding about the gene and the disease.
prostate carcinoma (37 papers, 2007 to 2025). A carcinoma that arises from epithelial cells of the prostate gland. "For the multivariate analysis, high STAT5a expression was significantly associated with poor overall survival in prostate cancer (lnHR = 0.736 [0.1906, 1.281], P-value = 0.00818)." (PMID 37369132, 2023). "For the univariate analysis, high STAT5a expression was significantly associated with poor overall survival in prostate cancer (lnHR = 0.6987 [0.1553;1.242], P-value = 0.0117)." (PMID 37369132, 2023). "Stat5a/b is constantly active in human prostate cancer, associated with high histological grades, and a predictor of early prostate cancer recurrence." (PMID 31835700, 2019). "STAT5a/b activation has been previously associated with increased migration and invasion, suppression of cell surface expression of E-cadherin and metastatic dissemination of prostate cancer cells." (PMID 24167634, 2013). "Previous studies demonstrate that both the genetic knockdown and pharmacological inhibition of STAT5A/B partially suppresses DNA repair, thereby augmenting radiotherapy efficacy in prostate cancer cell lines." (PMID 40723262, 2025). "In prostate cancer cells, similar interactions between AR and STAT5a/b signaling were shown and in hepatocellular cancer, CBG expression is regulated via the pioneer factors FOXA1 and the estrogen receptor, potentially underlying sex differences in CBG." (PMID 39240718, 2024). "In prostate cancer and Bcr-Abl-driven leukemia, researcher sought to identify small molecule inhibitors of Stat5a/b for lead optimization and therapy development." (PMID 38124049, 2023). "Among various causes of prostate cancer androgen receptor (AR) signaling, PTEN/PI3K/AKT/mTOR pathway, IL6/STAT3 and STAT5a/b are the most common pathways involved in prostate cancer cell survival and resistance." (PMID 36648960, 2023). "In contrast, STAT5a low-expressing patients had more favorable overall survival than high-expressing patients in hematological, ovarian, and prostate cancer patients." (PMID 37369132, 2023). "STAT5A has been reported to drive oncogenesis in many malignancies including lung cancer, prostate cancer, gastric cancer, and ductal carcinoma in situ." (PMID 35502613, 2022). "revealing the significant clinical potential of circ_0086722 in prostate cancer therapy, and circ_0086722 has been shown to drive prostate cancer development through the miR‐339‐5p/STAT5A axis." (PMID 35592755, 2022). "Prostate cancer distant clinical metastases were overexpressed with nuclear STAT5A/5B in 61% of cases, which consequently made prostate cancer cells migrate and invade more readily with the aid of microtubule network rearrangement." (PMID 36524006, 2022). "Nuclear STAT5A/5B expression predicted early disease recurrence and enhanced the ability of prostate cancer cells to metastasize in vivo and in vitro." (PMID 36524006, 2022). "Phenotypic analysis of TRAM mouse models of prostate cancer and STAT5 knockout mice indicated that STAT5A/5B activation was essential for the growth and survival of prostate cancer." (PMID 36524006, 2022). "Aberrant STAT5A expression has been reported in a number of different cancers, including breast, colon, head and neck, and prostate cancer as well as leukemia." (PMID 32641122, 2020). "In clinical specimens of human prostate cancer, the STAT5a/b gene locus was shown to undergo amplification during prostate cancer progression towards metastatic CRPC." (PMID 31269779, 2019). "Additional studies demonstrate that STAT5A/B signaling in prostate cancer and squamous cell carcinoma of the head and neck drive EMT programming, which results in enhanced cell migration, invasion, and formation of metastases." (PMID 31684144, 2019). "In vivo, Stat5a/b inhibition blocks prostate cancer subcutaneous and orthotopic xenograft tumour growth in nude mice." (PMID 31835700, 2019). "Transcription factor Stat5a/b has been shown to regulate the viability and growth of human prostate cancer cells." (PMID 31835700, 2019).
prostate carcinoma (continued). "From these profiles, previously published observations of high STAT5A activity in CR prostate cancer were confirmed." (PMID 23675504, 2013). "Further, we detected higher phosphorylation levels of the STAT5A substrate by hypoxic prostate carcinoma cells than by the normoxic counterpart." (PMID 23675504, 2013). "By using this novel peptide substrate microarray method we revealed high kinase activity mediated by signal transducer and activator of transcription 5A (STAT5A) in CR prostate cancer." (PMID 23675504, 2013). "In prostate cancer, differential STAT5a and STAT5b protein expression can be correlated with metastatic potential." (PMID 19630967, 2009). "Importantly, loss of AR resulted in an enhanced expression of PAX6, which reprogramed the lineage plasticity of prostate cancer cells to develop NE phenotypes through the MET/STAT5A signaling pathway." (PMID 38745318, 2024). "Moreover, the study has shown that the expression of unphosphorylated STAT5a inhibits tumor growth in mouse xenographs, and that down-regulation of STAT5 or HP1α expression in prostate cancer patients is associated with poor disease-free survival." (PMID 37369132, 2023). "Moreover, STAT5A/5B participated in the regulation of DNA repair using homologous recombination in prostate cancer by inducing the RAD51 mRNA level while blocking of JAK2-STAT5A/5B signal pathway sensitized prostate cancer to radiotherapy." (PMID 36524006, 2022). "Indeed STAT5A/B locus focal amplification was shown to be sufficient to elicit a growth advantage and disease progression in prostate cancer, and similarly here, the STAT3/5 genetic locus was amplified to enhance STAT3/5 expression." (PMID 36341492, 2022). "However, while serving as a potential marker of adaptive immune function, STAT5A activity and overexpression predict both early recurrence and tumor aggression in head and neck carcinoma, as well as prostate cancer patients, matching our findings in VS." (PMID 36195959, 2022). "In various preclinical models of prostate cancer, STAT5A/B (hereafter referred to as STAT5 unless specifically discriminated for gene product) has been shown to be critical for cell survival and proliferation through both androgen-dependent and androgen-independent mechanisms." (PMID 31269779, 2019). "However, Nevalainen and colleagues reported that STAT5B induces stem cell properties in prostate cancer cells in line with the increase in nuclear STAT5A/B observed in these tumors in correlation with bad prognosis." (PMID 31557897, 2019). "Since increased STAT5A kinase activity was generated by exposing prostate carcinoma cells to hypoxia, we propose that long-term ADT may induce tumor hypoxia and stimulate STAT5A kinase activity, which subsequently may lead to renewed, CR tumor growth." (PMID 23675504, 2013). "Our study verified the increased STAT5A-mediated kinase activity in CR prostate cancer xenografts." (PMID 23675504, 2013). "Hence, the study detected STAT5A as a candidate to be further investigated for its potential as marker of advanced prostate cancer and as possible therapeutic target protein." (PMID 23675504, 2013). "rs12601982 residing in the intron of the STAT5A gene is located in the same LD block as the reported loci (r2 = 0.98), suggesting that this region may be a promising common prostate cancer marker in different ethnic populations." (PMID 23668334, 2013). "Upon examination of a series of 80 prostate cancer specimens, autocrine prolactin immunostaining was positive in 54% of samples and local prolactin levels positively correlated with both high Gleason scores and activation of Stat5a/b, the major downstream signaling protein from the PRLRLF to growth." (PMID 33179012, 2020). "Moreover, in vitro inhibition of Stat5a/b induces apoptosis in human prostate cancer cells." (PMID 31835700, 2019).
prostate carcinoma (continued). "Similarly, in a limited population of prostate cancer patients studied, low phosphorylation levels of the STAT5A substrate by tumors from ADT-naïve patients’ were revealed, whereas the STAT5A phosphorylation level generated by the tumor from an early CR disease case was substantially higher." (PMID 23675504, 2013). "Knockdown of Twist1, an EMT marker, in prostate cancer cells, resulted in the suppression of the STAT5A/B signaling that can induce EMT phenotype and sphere formation ability in prostate cancer." (PMID 36969009, 2023). "The presence of positive feedback regulatory loop SNHG17/miR-339-5p/STAT5A/SNHG17 and SNORA71B in prostate cancer can promote cellular EMT and thus facilitate cancer progress." (PMID 36185210, 2022). "Conversely, inhibition of STAT5a/b depletes RAD51 levels, disrupting HR DNA repair, and sensitizing prostate cancer to radiation." (PMID 31993371, 2019). "To exclude that the finding of hypoxia-induced increased STAT5A activity was cell-line specific we analyzed two additional cell lines, the PC3 and DU145 prostate cancer cell lines, revealing similar results as in the 22Rv1 cell line." (PMID 23675504, 2013). "The current study identified increased phosphorylation level of the STAT5A peptide substrate by ADL and CR prostate carcinoma xenografts, compared to by ADT-naïve xenografts." (PMID 23675504, 2013). "The clinical and functional implications of transcription factor STAT5A/B and STAT3 have been well established in prostate cancer." (PMID 23668334, 2013). "Mechanistically, SNHG17 and its homolog SNORA71B were transactivated by signal transducer and activator of transcription 5A (STAT5A), and SNHG17 sponged with miR-339-5p and released the expression of STAT5A, thereby forming a regulatory loop and exacerbating prostate cancer progression." (PMID 35864871, 2022). "Stat5a/b is a critical inducer of RAD51 and HR DNA repair in prostate cancer." (PMID 34716319, 2021). "Hypoxia-mediated activation of STAT5A signaling has to our knowledge not been reported in prostate cancer." (PMID 23675504, 2013). "STAT5a is expressed in nonmetastatic C1D mouse prostate cancer cells, but not in their metastatic C2H counterparts, whereas STAT5b is expressed in both." (PMID 19630967, 2009). "Additionally, STAT5a is expressed in LNCaP human prostate cancer cells but not the more highly migratory PC-3 prostate cancer cell line, but STAT5b levels are comparable." (PMID 19630967, 2009).
leukemia (34 papers, 2009 to 2025). A malignant (clonal) hematologic disorder, involving hematopoietic stem cells and characterized by the presence of primitive or atypical myeloid or lymphoid cells in the bone marrow and the blood. "Mutations in STAT5A leading to its constitutive activation and formation of stable tetramers have been associated with multilineage leukemias." (PMID 39169031, 2024). "STAT5B has been defined as more important than STAT5A in BCR/ABL-induced leukemia, explaining the high frequency of STAT5B mutations in hematopoietic malignancies." (PMID 34055801, 2021). "We have identified the transcription factors STAT5A/B as critical nodes in the signaling network downstream of the leukemia-associated BCR/ABL oncogene." (PMID 30679796, 2019). "Here, we investigated the role of STAT5 isoforms in BCR/ABL+ leukemia, a disease that ceases upon combined loss of STAT5A and STAT5B." (PMID 30679796, 2019). "In line, Stat5b−/− leukemic cells induced leukemia with a significantly prolonged disease onset, whereas Stat5a−/− cells rapidly caused a fatal disease superimposable to wild-type cells." (PMID 30679796, 2019). "Super-enhancer regulating leukemia associated genes such as STAT5A and GATA2 also showed enrichment of STAT5A and GATA2, respectively." (PMID 28526829, 2017). "Furthermore, cSTAT5 in hematopoietic stem cells (HSC) was shown to be crucial for development of leukemia and knock-down of STAT5A was associated with inhibiting growth of CML CD34+ cell from patients with acquired resistances towards TKI." (PMID 25333255, 2014). "Thus, hyperactivity of STAT5 as mimicked by expression of a constitutively activated STAT5A (cSTAT5A) variant suffices to induce a multilineage leukemia upon transplantation." (PMID 25333255, 2014). "Its cell-permeable prodrug 17 (dubbed Pomstafib-2-CR) inhibits phosphorylation of STAT5b in cultured human leukemia cells with slightly higher activity and selectivity over STAT5a than Pomstafib-2, the prodrug corresponding to Stafib-2." (PMID 41320753, 2025). "Despite STAT5A/5B being active in most leukemia and some solid tumors, the role of STAT5A/5B in tumor invasion was complicated." (PMID 36524006, 2022). "This aberrant STAT5A phosphorylation licenses translocation to the nucleus to drive target gene transcription, resulting in a hyperproliferative state necessary for leukemia cell survival." (PMID 34263728, 2021). "DOT1L inhibition reduces STAT5A activation and downregulates STAT5A targets in FLT3-ITD leukemia lines." (PMID 34263728, 2021). "Our observations suggest that most of the toxicity from low-dose DOT1L inhibition in MLL-r, FLT3-ITD+ leukemia cell lines stems from downregulation of FLT3 and subsequent loss of STAT5A phosphorylation." (PMID 34263728, 2021). "To further interrogate the H3K79me2-dependence of leukemia survival on FLT3-ITD/STAT5A signaling, we sought to ectopically restore this signaling pathway upon DOT1L inhibition to potentially rescue viability." (PMID 34263728, 2021). "A phosphonate prodrug based on Stafia‐1 inhibited STAT5a with selectivity over STAT5b in human leukemia cells, providing the first demonstration of selective in vitro and intracellular inhibition of STAT5a by a small‐molecule inhibitor." (PMID 31503360, 2020). "Elevated levels of STAT5A/B contribute to a higher resistance rate to TK inhibitors in BCR–ABL+ leukemia." (PMID 31690038, 2019). "Transgenic mouse models expressing either wt Stat5b, or ca Stat5a or ca Stat5b in hematopoietic lineages were used to study the role of STAT5A/B in leukemia." (PMID 31690038, 2019). "In mice, the expression of a constitutively active (ca) version of STAT5A (caSTAT5A) induces an aggressive multi-lineage leukemia." (PMID 30679796, 2019). "Even LSCs require STAT5A/B signaling—lowering STAT5A/B levels in an already established leukemia blocks the disease and disables BCR–ABL+ LSCs." (PMID 31690038, 2019).
leukemia (continued). "Several proximal super-enhancers were found to be located at leukemia-associated genes such as GATA2, STAT5A/B, and ZEB2, as expected of super-enhancers found in a leukemia cell line." (PMID 28526829, 2017). "In particular, STAT5S779 phosphorylation has been identified as a prerequisite for STAT5A to translocate into the nucleus and nuclear accumulation of STAT5A is prevented by PAK I group kinase inhibitors in BCR-ABL1+ leukemias." (PMID 25333255, 2014). "Of the seven STAT family members (STAT1-STAT6, with two independent genes encoded STAT5A and STAT5B), STAT3, as well as STAT5 to some extent, are most frequently activated in quite a lot human solid tumors and leukemias." (PMID 23704931, 2013). "An increase of STAT5A expression plays a vital role in leukemia development." (PMID 36561735, 2022). "It is possible that the dependence of MLL-r, FLT3-ITD+ leukemia on FLT3-ITD expression may be due to HOXA9 requiring STAT5A and/or PBX3 and C/EBPA to cooperatively bind select target genes." (PMID 34263728, 2021). "To test whether the effect extends to human BCR/ABL+ leukemia, we ablated STAT5A or STAT5B via shRNA-mediated knockdowns in K562 cells." (PMID 30679796, 2019). "In leukemia, STAT5A and STAT5B may have individual functions as the constitutive activation of either protein is capable to inflict a disease of a specific phenotype." (PMID 30679796, 2019). "STAT5A silencing instead leads to better chemotherapy response in leukemia." (PMID 24400121, 2014). "Several lines of evidence argue for a critical role of STAT5A/B in leukemia." (PMID 25333255, 2014). "Our findings showed that STAT5, more particularly, STAT5a, plays a critical role in TA regulation, suggesting that inhibition of STAT5a in combination with BCR-ABL may provide an alternative approach for treatment of leukaemia, especially in patients who are resistant to tyrosine inhibitors." (PMID 22151181, 2011). "Among the various members, STAT3 and STAT5 (which has two isoforms, called STAT5A and STAT5B) were the proteins chosen as targets for the development of PROTACs for the treatment of leukemia." (PMID 38845697, 2024). "ChIP–seq profiling of Stat5a, Runx1 and Runx2 confirmed the motif analysis, demonstrating cobinding of these transcription factors and BAF or MLL1 and MLL4 complexes at key pro-leukemia genes including Hoxa7 and Hoxa9." (PMID 37580596, 2023). "STAT5A/B acts as critical node in the signaling network downstream of BCR–ABL and is indispensable for initiation and maintenance of BCR–ABL+ leukemia." (PMID 31690038, 2019). "Data were compared to transcriptomes of various other human leukemia models we had generated over the years, including CB CD34+ cells transduced with MLL-AF9, FLT3-ITD, NUP98-HOXA9, STAT5A and KRASG12V." (PMID 27055152, 2016). "Finally, the data provide molecular evidence that STAT5B may represent a specific therapeutic target in BCR-ABL-positive leukemia although the development of STAT5B-specific small molecule inhibitors may be difficult due to the high homology between STAT5A and STAT5B." (PMID 24836440, 2014). "The two transcription factors STAT5A and STAT5B are central signaling molecules in leukemias driven by Abelson fusion tyrosine kinases and they fulfill all criteria of drug targets." (PMID 25333255, 2014). "In BCR-ABL1+ leukemias, STAT5A mutants lacking serine phosphorylation on S725 and S779 strongly impaired the viability of the leukemic cells and did not support transformation by Abelson oncogenes." (PMID 25333255, 2014). "Thus, AG-490 suppresses several signaling pathways, including IL-2-mediated signaling, which is upstream of JAK3 and STAT5A and B. Generally, AG-490 can be used to control the abnormal constitutive activation of JAK2 in leukemia cell lines." (PMID 24170986, 2013).
leukemia (continued). "Moreover, chromatin accessibility profiling of leukemia cells disrupted for cBAF (Smarcd2 knockout), MLL1 (Kmt2a knockout) or MLL4 (Kmt2d knockout) showed that these chromatin factors are required to maintain optimal accessibility at the Stat5a and Runx2 binding loci." (PMID 37580596, 2023). "Our previous targets additionally explored the Bcr-Abl oncogene and the transcription factor STAT5A in control of leukemic cell growth using similar non-viral techniques, so that the proposed delivery system could be a fruitful platform in RNAi-mediated leukemia therapy in general." (PMID 39858509, 2025). "More recently, dissection of the respective contributions of STAT5A and STAT5B in BCR-ABL-dependent transformation revealed that STAT5B, but not STAT5A, is a critical effector of BCR-ABL-driven leukemia development." (PMID 31963765, 2020). "Whilst CaMKII does not phosphorylate STAT5a at the site examined in this study, a FAK-mediated pathway can control STAT5 activation in leukaemia cells." (PMID 27605043, 2016). "In non-MLL-rearranged leukemia, such as Npm1c/Flt3-ITD, we have also demonstrated a role for leukemia-specific interactions of COMPASS complexes with TFs resulting in altered accessibility at Stat5a and Runx2 loci and consequent transcriptional dysregulation." (PMID 40523422, 2025). "We observed reductions in H3K79me2 and STAT5A phosphorylation after 9 days pinometostat treatment, suggesting that DOT1L inhibition may also reduce the viability of non-MLL-rearranged FLT-ITD leukemias through disruption of FLT3-ITD/STAT5A signaling." (PMID 34263728, 2021).